ALOX15 (arachidonate 15-lipoxygenase)
Diseases named in the same sentence as ALOX15 in open-access papers (continued):
Sharing a sentence is not in itself a finding about the gene and the disease.
gastric cancer (26 papers, 2020 to 2025). A primary or metastatic malignant neoplasm involving the stomach. "CAF-derived exosomal miR-522 inhibits ferroptosis of gastric cancer cells by targeting ALOX15 (encoding arachidonate 15-lipoxygenase) and decreasing lipid-reactive oxygen species (ROS) accumulation, thereby inducing chemoresistance of gastric cancer cells." (PMID 36635302, 2023). "Moreover, cancer-associated fibroblasts confer chemoresistance to gastric cancer via the secretion of miR-522, which suppresses ALOX15 expression and impedes the accumulation of lipid ROS in tumor cells." (PMID 39043653, 2024). "Notably, exosomes microRNA-522 (miR-522), derived from cancer-associated fibroblasts (CAFs), has been implicated in the acquisition of chemoresistance in gastric cancer (GC) cells by modulating the ALOX15 pathway and impeding lipid-ROS accumulation, as demonstrated both in vitro and in vivo." (PMID 40485724, 2025). "Studies have shown that down-regulation of ALOX15 during tumorigenesis may enhance the association between colitis and colorectal tumorigenesis, and ALOX15 is able to significantly promote ferroptosis and inhibit proliferation of gastric cancer cells." (PMID 39845670, 2024). "For the treatment of gastric cancer (GC), cisplatin and paclitaxel promoted cancer-associated fibroblasts (CAFs) to secrete exosomal miR-522, leading to decreased ALOX15 and ROS levels and ferroptosis suppression." (PMID 36672245, 2023). "CAF-derived exosomal microRNA-522 attenuates ferroptosis by down-regulating Arachidonate 15-lipoxygenase (ALOX15), thus provoking acquired cisplatin resistance in gastric cancer." (PMID 40740652, 2025). "For instance, CAFs can release exosomal miR-522, which suppresses ferroptosis in gastric cancer by inhibiting arachidonate 15-lipoxygenase (ALOX15), a key lipid-ROS generator." (PMID 40427384, 2025). "This study demonstrated that CAFs inhibit ALOX15 expression in gastric cancer cells via exosomal miR-522, thereby reducing lipid ROS accumulation, suppressing ferroptosis, and promoting chemoresistance." (PMID 40485724, 2025). "For example, CAF-secreted miR-522 binds to 15-lipoxygenase (ALOX15) mRNA, inhibiting lipid peroxidation and reducing ferroptosis in gastric cancer cells." (PMID 41229433, 2025). "By dampening ALOX15 translation, CAFs indirectly shield gastric cancer cells from ferroptotic death." (PMID 38217037, 2024). "Exosome-mir-522 in CAF inhibits ferroptosis and promotes the acquisition of chemical resistance in gastric cancer by targeting ALOX15 and blocking lipid ROS accumulation." (PMID 38402311, 2024). "Through secreting exosomes, CAFs was demonstrated to inhibit ferroptosis in gastric cancer cells by miR-522-mediated targeting arachidonate lipoxygenase 15 (ALOX15) and blocking lipid reactive oxygen species (ROS) accumulation and induce chemoresistance." (PMID 38802766, 2024). "A recent discovery pinpointed a nuanced strategy wherein CAFs secrete exosome-derived miR-522, which post-transcriptionally inhibits the translation of ALOX15 mRNA in gastric cancer cells." (PMID 38217037, 2024). "Clinical evidence shows that ALOX15 is closely related to the production of lipid ROS in gastric cancer." (PMID 36187333, 2022). "Targeting ALOX15 and blocking of subsequent reactive oxygen species (ROS) accumulation can inhibit ferroptosis in gastric cancer cells." (PMID 36313765, 2022). "This leads to ALOX15 inhibition and a decrease in the level of lipid ROS in cancer cells, which is also related to the acquisition of drug resistance in gastric cancer." (PMID 36187333, 2022). "When miR-522 acts on ALOX15, the activity of ALOX15 is inhibited and reduces the accumulation of lipid ROS in cancer cells, thus improving the ferroptosis of gastric cancer cells." (PMID 36187333, 2022). "In gastric cancer cells, CAFs secrete exosome miR-522 to inhibit ferroptosis by targeting ALOX15 and blocking lipid-ROS accumulation." (PMID 34485394, 2021).
gastric cancer (continued). "Exosomal miR-522 secreted by TAFs prevents the lipid ROS accumulation and ferroptosis by inhibiting the ALOX15 activity, which explains the abnormality of ALOX15 in gastric cancer." (PMID 37287758, 2021). "Cisplatin and paclitaxel promote miR-522 secretion which decreases the accumulation of lipid-ROS by suppressing ALOX15 expression and ultimately results in chemoresistance in gastric cancer." (PMID 35047016, 2021). "CAFs-derived exosomal miR-522 reduces the contents of lipid-ROS in gastric cancer cells by inhibiting the expression of ALOX15, which leads to a decrease in the sensitivity of gastric cancer to chemotherapy." (PMID 32299469, 2020). "Here, we provide clinical evidence to show that arachidonate lipoxygenase 15 (ALOX15) is closely related with lipid-ROS production in gastric cancer, and that exosome-miR-522 serves as a potential inhibitor of ALOX15." (PMID 32106859, 2020). "Interestingly, cisplatin and paclitaxel can elevate ferroptosis levels in gastric cancer cells via the USP7/hnRNPA1/miR-522/ALOX15 axis, thereby enhancing chemosensitivity." (PMID 41229433, 2025). "Likewise, PLIN2 expression contributed to a decreased arachidonate 15-lipoxygenase (ALOX15) expression and arrested the occurrence of ferroptosis in gastric cancer." (PMID 36591531, 2022). "ALOX15 (arachidonate lipoxygenase 15) is related to producing lipid-ROS in gastric cancer." (PMID 33672990, 2021). "High levels of ALOX15 protein are also associated with better overall survival (OS) of gastric cancer patients, suggesting that ALOX15 acts as an anti-cancer factor in GC." (PMID 32106859, 2020). "The expression pattern of ALOX15 was validated in 12 gastric cancer patients, and ALXO15 protein showed an overall downward trend, but ALOX15 mRNA had no evident changes." (PMID 32106859, 2020).
diabetes (23 papers, 2013 to 2025). "The most up-regulated transcript in iron-deficient pancreas was arachidonate 15-lipoxygenase (Alox15), which has been implicated in the development of diabetes." (PMID 24465846, 2014). "As elevation in ALOX15 or its metabolites has been associated with increased risk of atherogenesis, metabolic dysfunction–associated steatotic liver disease, diabetes, stroke, Alzheimer’s disease, and breast and prostate cancer, detailed rephenotyping was performed." (PMID 39436697, 2024). "Overall, these data raise the possibility that Reg expression may serve as a biomarker for iron-related pancreatic stress, and that iron deficiency may adversely affect the risk of developing diabetes through up-regulation of Alox15." (PMID 24465846, 2014). "Our observation that iron deficiency causes a marked elevation in Alox15 mRNA and protein levels in the pancreas raises the possibility that iron deficiency—in addition to iron overload—may increase the risk of developing diabetes through up-regulation of Alox15." (PMID 24465846, 2014). "Prior studies demonstrated that whole-body deletion of mouse Alox15 protects against diabetes induced by the chemical streptozotocin (STZ)." (PMID 39531315, 2024). "In most of these studies, loss-of-function strategies were employed to evaluate the role of ALOX15 in the pathogenesis of obesity and diabetes, but the application of gain-of-function strategies was rare." (PMID 36902243, 2023). "For example, studies of global Alox15−/− mice reveal that they are resistant to streptozotocin (STZ)-induced diabetes." (PMID 35448529, 2022). "Strikingly, these mice are protected from the development of diabetes when Alox15 is genetically deleted." (PMID 34064822, 2021). "In support of this contention, protection from diabetes following STZ delivery was also seen in mice with a pancreas-specific knockout of Alox15." (PMID 34064822, 2021). "Pancreas Fe deficiency results in upregulated transcription of arachidonate 15-lipoxygenase (Alox15), a molecule involved in the development of diabetes." (PMID 30746586, 2019). "In the pancreas, Alox15 is present in beta cells where it appears to play a role in the pathogenesis of diabetes." (PMID 24465846, 2014). "When Alox15 is specifically deleted in islets of mixed background mice, these mice are protected from developing type 1-like diabetes following streptozotocin treatment." (PMID 23437231, 2013). "We previously showed that the Alox15 gene locus contributes to diabetes pathogenesis in the NOD model using a congenic strain lacking Alox15 (NOD-Alox15null)." (PMID 23437231, 2013). "Our multi-omics study points to an involvement of reduced ALOX15 levels and an associated lack of eicosanoid switching as mechanisms contributing to a proinflammatory milieu in the lungs of subjects with diabetes mellitus." (PMID 38900131, 2024). "Studies have shown that ALOX15 and its related products are widely distributed in human tissues and related to multiple diseases such as liver, cardiovascular, cerebrovascular diseases, diabetes mellitus and other diseases." (PMID 37849828, 2023). "Indeed, similar to what was observed in the whole body knockout, specific inactivation of Alox15 in the pancreas using Pdx1-Cre was protective against STZ-induced diabetes and improved glucose homeostasis during high-fat diet (HFD) feeding." (PMID 35448529, 2022). "Alox15 deletion leads to 98 percent protection from diabetes in female NOD mice." (PMID 23437231, 2013). "ALOX5 and ALOX15 are major contributions to the generation of lipid peroxides; thus, their overexpression is related to diseases such as systemic sclerosis, certain types of cancers, and diabetes, moreover affecting inflammation and promoting lipid peroxides formation." (PMID 37569384, 2023). "However, this diabetes mellitus mouse model does not show any decline in kidney function; thus, the mechanism on how ALOX15 is associated with impaired kidney function in CKD models has remained unclear." (PMID 33595729, 2021).
diabetes (continued). "Furthermore, Reg expression may serve as a biomarker for iron-related pancreatic stress, as iron changes may contribute to diabetes development through up-regulation of Alox15." (PMID 26302420, 2015). "In order to characterize the mechanism of protection from diabetes progression in NOD- Alox15 null mice, we first investigated several aspects of the timing and cellular location of the Alox15 gene expression in NOD mice, and how alterations in expression might affect inflammation." (PMID 23437231, 2013). "Myeloid-specific deletion of Alox15 in NOD mice led to reduced macrophage infiltration into the islet, preserved β-cell mass, and protection from diabetes." (PMID 34064822, 2021). "Whole-body deletion of Alox15 on the autoimmune non-obese diabetic (NOD) mouse background results in almost complete protection against diabetes." (PMID 39531315, 2024). "However, Alox15 also plays a role in the regulation of adipose tissue and development of insulin resistance, and a reduction in Alox15 expression has been shown to improve neuropathy in mice with STZ-induced diabetes." (PMID 38933596, 2024).
breast carcinoma (21 papers, 2008 to 2024). "Elevated levels of ALOX15 and its resulting metabolites have been associated with breast cancer and Alzheimer’s disease." (PMID 39436697, 2024). "In in vitro assays, the major ALOX15 metabolite, 13‐S‐hydroxyoctadecadienoic acid, demonstrated dose‐ and time‐dependent inhibition of breast cancer growth." (PMID 38140764, 2024). "ALOX15 mediates lymphatic vessel invasion and lymph node metastasis in human breast cancer xenograft mouse." (PMID 34059009, 2021). "The results obtained from this research indicate that targeting ALOX15 could be a potential avenue for treating breast cancer." (PMID 38516826, 2024). "Similarly, ALOX15 is transcriptionally downregulated in DOX‐resistant breast cancer cells, and its overexpression in resistant cells leads to resensitization to DOX." (PMID 38140764, 2024). "For example, in breast cancer, downregulation of ALOX15 expression has been reported in52,53." (PMID 31534156, 2019). "Consequently, Alox15 depletion resulted in reduced LN metastasis in a xenograft model of breast cancer, and Alox15 expression in LN metastasis correlated with secondary metastasis in breast cancer patients." (PMID 34685565, 2021). "For example, downregulation of arachidonate 15-lipoxygenase (ALOX15) has been reported to enhance sensitivity to cisplatin and paclitaxel in breast cancer." (PMID 39045454, 2024). "The inclusion of these 8 genes (ALOX15, CHAC1, CISD1, CS, SLC7A11, EMC2, G6PD, and ACSF2) is highly valuable for prognostic prediction in breast cancer patients." (PMID 39867656, 2024). "Building on this foundation, a recent study introduced a novel prognostic model for breast cancer, that integrates four ferroptosis-related genes (CISD1, ALOX15, CARS1, and SLC7A11)." (PMID 39867656, 2024). "The analysis of the GEPIA dataset revealed that ALOX15, ALOXE3, and HO‐1 exhibited higher expression levels, while ALOX12 showed lower expression levels in breast cancer tissues compared to normal tissues." (PMID 38516826, 2024). "In the lymph node metastases of breast cancer patients, the production of 12(S)-HETE correlates directly with increased ALOX15 expression and inversely with metastasis-free survival." (PMID 28013338, 2017). "In breast cancer, SBFI26, an inhibitor of FABP5, induces ferroptosis by elevating levels of ferrous ions and lipid peroxidation, increasing the expression of ALOXE3, ALOX5, and ALOX15, thus driving ferroptosis in tumor cells." (PMID 39633985, 2024). "The results revealed that breast cancer tissues exhibited lower expression levels of SAT1, ALOX5, ALOX12, ATF3, ATF4, GPX4 and NFE2L2 compared to normal tissues; conversely, higher expression levels of ALOX15, ALOXE3 and HO‐1 were observed in breast cancer tissues than in normal tissues." (PMID 38516826, 2024). "We selected two cell lines that do not express the human ALOX15 gene, including a vimentin-expressing mouse fibroblast cell line (NIH3T3) and a human breast cancer cell line (MCF-7), a vimentin-lacking cell lines." (PMID 22879973, 2012).
colon cancer (20 papers, 2008 to 2025). "ADIPOQ, ALOX5, and ALOX15 are reportedly associated with lung cancer, colorectal cancer, and colon cancer." (PMID 30071629, 2018). "The expression of 15-lipoxygenase-1 (ALOX15), which plays a tumor-suppressing role, is reduced in human cancers, particularly colon cancer." (PMID 39334689, 2024). "Global H3 and H4 acetylation, as well as demethylation of the CpG islands on the 5′ promoter region, have been shown to upregulate Alox15 gene expression in colon cancer cells." (PMID 29235036, 2018). "Activation of the cyclic GMP/protein kinase G pathway also induces Alox15 expression in human colon cancer cells." (PMID 29235036, 2018). "This is consistent with a previous study, which reported a role of p300 HAT in Alox15 expression in colon cancer cells." (PMID 29235036, 2018). "The current study didn’t observe evidence of interaction between variant alleles of SNPs in previously reported genes- ALOX15, IL16, MDR1, NFkB, PTGS1 and PTGS2- with aspirin only use and CRC or colon cancer risk." (PMID 29425227, 2018). "Since presence of 5hmC in promoter would impact the level of transcription, our characterization of lower hydroxymethylated level in promoter of CRCs, provides a possible reason of down-regulation of ALOX15 in colon cancer." (PMID 27546520, 2016). "ALOX15 gene has decreased expression (downregulated) in colorectal tumorigenesis in colon cancer." (PMID 32986378, 2020). "Transgenic expression of ALOX15 suppresses TNF-α and iNOS expression as well as NF-κB activation and downregulates LRP5 to suppress Wnt/β-catenin signaling, thereby inhibiting colon cancer." (PMID 39334689, 2024). "15-lipoxygenase-1 (ALOX15 or 15-LOX-1), a member of the AA pathway, is involved in the formation of lipoxins and resolvins to resolve inflammation and cancer of the colon." (PMID 33348563, 2020).
prostate carcinoma (18 papers, 2008 to 2025). A carcinoma that arises from epithelial cells of the prostate gland. "This notion is reflected in prostate cancer, where ALOX15’s substrate preference to LA is reported along with differential effects of 15-HETE and 13-HODE." (PMID 36438817, 2022). "However, as there is an upregulation of ALOX15 in prostate carcinoma and both enzymes are capable of metabolizing AA and LA it is difficult to distinguish function between the two enzymes." (PMID 36438817, 2022). "ALOX5 and ALOX15 which convert DHA to resolvin Ds (RvDs) were highly expressed in prostate cancer." (PMID 32469149, 2020). "Similarly, 8-farnesyloxycoumarin decreased the viability of prostate cancer cells overexpressing ALOX15, and delphinidin (identified in Pelargonium) was shown to reduce ferroptosis and myocardial damage by suppressing ALOX15 expression both in vitro and in vivo." (PMID 40807372, 2025). "While normal prostate epithelium expresses ALOX15B but not ALOX15 in the luminal compartment, expression of ALOX15B was lost in prostate cancer as well as associated cell lines, and also 15-HETE production was found to be reduced." (PMID 36438817, 2022).
colorectal cancer (17 papers, 2008 to 2024). A primary or metastatic malignant neoplasm that affects the colon or rectum. "It has been found that ALOX15 can regulate the sensitivity of colorectal cancer cells to ionizing radiation, which can help patients overcome tumor radiation resistance." (PMID 39845670, 2024). "Few studies stating otherwise have demonstrated significant overexpression of ALOX15 and its metabolite in human colorectal cancer epithelial cells compared to normal tissue." (PMID 38612771, 2024). "Similar to early events in the development of pancreatic cancers, expression of the ALOX15 gene is significantly downregulated in human colorectal cancers." (PMID 38612771, 2024). "Tumor environments exhibit fluctuating expressions of ALOX15 across a broad range of tissues: while it is abundantly present in cancerous tissues of the breast, prostate, lung, head and neck, and colorectal cancers, its expression is lost in tumors of the brain, muscle, or germline cells." (PMID 38612771, 2024). "Furthermore, downregulation of PPAR-γ by the ALOX15 product 13-S-HODE sensitizes apoptotic signaling pathway in colorectal cancer cells." (PMID 38612771, 2024). "ALOX15’s gene expression is down-regulated in colorectal cancer (CRC)." (PMID 32986357, 2020). "Subsequently, we screened four genes (ALOX15, GHRHR, TFPI2 and TKTL1) with aberrant methylation and aberrant hydroxymethylation at some genome position by functional enrichment analysis as candidate genes associated with colorectal cancer." (PMID 27546520, 2016). "Consistently, SELENOI was significantly upregulated in human colorectal cancer tissues, while PLA2G2A, PLA2G5, and ALOX15 were significantly downregulated." (PMID 38757622, 2024). "Gene expression of ALOX15 suppresses the TNF-α signaling pathway, IL-1β/NF-κB, and IL-6/STAT3, which play a major role in increasing colorectal cancer through chronic inflammation." (PMID 32986357, 2020). "To confirm whether LXA4-synthesizing enzymes are dysregulated in colorectal cancer, we detected the expressions of ALOX5, ALOX12, ALOX15 and ALOX15B in colorectal cancer tissue." (PMID 31528237, 2019). "As a result, ALOX5 and ALOX12 were strikingly up-regulated in colorectal polyp, compared with those in colorectal cancer surrounding tissue, while there were no significant change in the expressions of ALOX15 and ALOX15B." (PMID 31528237, 2019). "Furthermore, the expressions of LXA4-synthesizing enzymes ALOX15 and ALOX15B were down-regulated in colorectal cancer." (PMID 31528237, 2019).